ZNF669 (zinc finger protein 669)
Description:
May be involved in transcriptional regulation.
Synonyms: FLJ12606
Tractability: PROTAC: ubiquitination databases record sites on it.
Gene: Protein-coding gene on chromosome 1 (247,099,962 to 247,104,372, reverse strand). Ensembl gene ENSG00000188295.
Subcellular location: Nucleus
Pathways (Reactome):
Gene expression (Transcription): Generic Transcription Pathway; Regulation of endogenous retroelements by KRAB-ZFP proteins
Gene Ontology:
Molecular function: protein binding; DNA-binding transcription factor activity, RNA polymerase II-specific; RNA polymerase II transcription regulatory region sequence-specific DNA binding
Biological process: regulation of transcription by RNA polymerase II; regulation of DNA-templated transcription
Cellular component: nucleus
Genetic constraint (gnomAD): Loss-of-function variants: 7 observed, 12.53 expected, observed/expected ratio (o/e) 0.56, 90% interval 0.32 to 1.05. The upper end of that interval is the gene's LOEUF score, 1.05, which puts it in group 4 of 6, group 1 being the genes least tolerant of losing a copy. Missense variants: 481 observed, 480.62 expected, observed/expected ratio (o/e) 1, 90% interval 0.93 to 1.08. Synonymous variants: 151 observed, 160.86 expected, observed/expected ratio (o/e) 0.94, 90% interval 0.82 to 1.07.
Homologues: Orthologues: chimpanzee ZNF669 (98% identical), macaque ZNF669 (90% identical), mouse Zfp78 (41% identical), Drosophila melanogaster CG3281 (32% identical), Drosophila melanogaster CG2712 (28% identical), Drosophila melanogaster Phs (25% identical). Paralogues in human: ZNF20 (48% identical), ZNF69 (47% identical), ZNF439 (47% identical), ZNF555 (46% identical), ZNF440 (46% identical), ZNF77 (46% identical), ZNF529 (46% identical), ZNF805 (45% identical), ZNF582 (45% identical), ZNF264 (44% identical), ZNF596 (44% identical), ZNF599 (44% identical), and 50 more.
Diseases named in the same sentence as ZNF669 in open-access papers:
ZNF669 is named in the same sentence as 1 disease in open-access papers, as found by Europe PMC text mining. Sharing a sentence is not in itself a finding about the gene and the disease.
ZNF669 shares sentences with these, for which no sentence is quoted: cancer (1 paper).